LINC02487 (long independently transcribed non-coding RNA 2487)
Gene: Long non-coding RNA gene on chromosome 6 (167,679,626 to 167,696,487, reverse strand). Ensembl gene ENSG00000203688.
Diseases named in the same sentence as LINC02487 in open-access papers:
LINC02487 is named in the same sentence as 1 disease in open-access papers, as found by Europe PMC text mining. Sharing a sentence is not in itself a finding about the gene and the disease.
LINC02487 shares sentences with these, for which no sentence is quoted: breast carcinoma (1 paper).